RNU6-770P (RNA, U6 small nuclear 770, pseudogene)
Gene: Small nuclear RNA gene on chromosome 6 (108,392,073 to 108,392,177, forward strand). Ensembl gene ENSG00000200799.
Homologues: Orthologues: macaque U6 (96% identical), rabbit U6 (77% identical), dog U6 (71% identical), mouse Gm25792 (69% identical), guinea pig U6 (62% identical), rat LOC120103222 (61% identical). Paralogues in human: RNU6-1084P (79% identical), RNU6-1316P (79% identical), RNU6-338P (79% identical), RNU6-98P (79% identical), RNU6-1031P (78% identical), RNU6-1145P (78% identical), RNU6-1214P (78% identical), RNU6-16P (78% identical), RNU6-235P (78% identical), RNU6-333P (78% identical), RNU6-38P (78% identical), RNU6-429P (78% identical), and 1287 more.